ADH1B (alcohol dehydrogenase 1B (class I), beta polypeptide)
Diseases named in the same sentence as ADH1B in open-access papers (continued):
Sharing a sentence is not in itself a finding about the gene and the disease.
tumor (52 papers, 2009 to 2026). "Gene expression of ADH1B in LUADs is associated with tumor development and decreases as tumor progresses." (PMID 37848457, 2023). "When we stratified the population into different tumor subsites, the associations between ADH1B, ALDH2, and OPSCC became more and more evident." (PMID 37706329, 2023). "Altogether these results indicate that the presence of ADH1B+ CAFs in the LUAD tissue is associated with the indolent behavior of the tumor and better overall survival of patients." (PMID 37848457, 2023). "In conclusion, we showed that ADH1B+ CAFs deficiency in early-stage LUADs is associated with tumor aggressive behavior." (PMID 37848457, 2023). "ADH1B + fibroblasts were the most common subtype in normal tissue (54% of fibroblasts) but were infrequent in tumours (5% of fibroblasts)." (PMID 39757146, 2025). "Specifically, in cluster 1, we found that the chemokine CCL19 produced by fibroblasts and markers of tumor-associated fibroblasts such as SFRP1, PI16, and ADH1B were significantly expressed." (PMID 40538442, 2025). "CA-II, ADH1C, CEH, IgGFc-binding protein, and ADH1B were all found to be less-abundant proteins in both regions of the tumor analyzed, suggesting their possible down-expression in CRC cells." (PMID 39195201, 2024). "In line with findings from TCGA, our dataset with 111 patients in replication demonstrated that the depression in tumor expression was most notable for ADH1B." (PMID 38256214, 2024). "In terms of exploring residual disease-related biomarkers, Anil K. Sood found that FABP4 and ADH1B were highly expressed in the tumor tissue of non-R0 patients." (PMID 38129848, 2023). "Taken together, our data identified ADH1B as a novel mesenchymal suppressor of tumor-promoting IL-6 overexpression." (PMID 37185128, 2023). "As we expected, the number of ADH1B+ fibroblasts in the tumor tissue of indolent LUADs was significantly higher (FC = 4.02, p < 0.05) in comparison to the aggressive group, supporting the results obtained using scRNAseq." (PMID 37848457, 2023). "The results indicated that ACSL3, ADH1B, ALDH2, and HADHA had strongly associated with the tumor grade." (PMID 37540213, 2023). "ADH1B expression is very specific for fibroblast-like cells in the LUAD tumor microenvironment that makes it one of the most important markers for the detection of ADH1B+ CAFs." (PMID 37848457, 2023). "We parsed apart separate subpopulations of CAFs in the tumor microenvironment and identified the association between the ADH1B+ CAF enrichment of LUAD at early stages and predicted tumor behavior." (PMID 37848457, 2023). "The mRNA expression of SDC1 and ADH1B were significantly lower in the tumor tissues when compared to the normal tissues, which were opposite at the protein levels through the HPA database." (PMID 35280985, 2022). "SDC1 and ADH1B were significantly expressed low in the normal tissues when compared to the tumor tissues, which were opposite at the protein level." (PMID 35280985, 2022). "Clustered stromal cells corresponded to endothelial cells (positive for PECAM1/CD31, VWF), normal fibroblasts (FN1, EGFL6), tumor-associated fibroblasts (TAFs; PDGFRA, ADH1B), and thymic epithelial cells (TECs; KRT19, S100A14)." (PMID 35869073, 2022). "ADH1B is involved in the metabolism of several anti-tumor drugs, including ifosfamide and cyclophosphamide." (PMID 35433681, 2022). "At the end of the experiment, the aggregate tumor weight of the mice injected with cells with ectopic ADH1B expression was significantly higher (~2.5-fold) than those of the mice injected with control cells (p < 0.01)." (PMID 29861857, 2018). "All cell lines had fairly low ADH1B expression, which prompted us to compare the ADH1B expression in tumor samples from mice injected with a cell line with the ADH1B expression in the same cell line in vitro." (PMID 29861857, 2018).
tumor (continued). "Investigating the upstream regulation of ADH1B, we examined several possibilities that can regulate gene expression under in vivo conditions and narrowed down the effect to hypoxic tumor micro-environment." (PMID 29861857, 2018). "ADH1B expression was significantly higher in the tumor samples than in the cell lines, suggesting that tumor microenvironmental factors increase ADH1B expression in vivo." (PMID 29861857, 2018). "The site specific analysis revealed, somewhat surprisingly, that the amino acid most consistently differentially phosphorylated in normal and tumor tissue was Y34 of alcohol dehydrogenase 1B, ADH1B ( less phosphorylated in tumors)." (PMID 19946374, 2009). "ADH1B may influence BCa progression through modulation of muscle-related functions and extracellular matrix organization, potentially affecting tumor stiffness and metastatic potential." (PMID 41001025, 2025). "Comparative expression analysis revealed that both SRPX and ADH1B were significantly downregulated in tumor tissues compared to normal bladder tissues (P < 0.05) across both training and validation cohorts, suggesting their potential protective roles in BCa pathogenesis." (PMID 41001025, 2025). "The levels of ADH1B expression exhibited a notable and consistent reduction in tumor tissue." (PMID 38256214, 2024). "Promoting the differentiation of CAFs into the ADH1B+ subtype may improve the anti-tumor immune effect." (PMID 37187731, 2023). "Promoting the differentiation of CAFs into the ADH1B+CAFs may contribute to enhancing anti-tumor immune response, while FAP+CAFs are specifically enriched in late-stage tumors and promote tumor growth." (PMID 37187731, 2023). "We have defined the top 5 marker genes (ADH1B, CFD (DF), SEPP1 (SELENOP), DCN, and A2M) that could be used for the identification of ADH1B+ CAFs in tumor tissues." (PMID 37848457, 2023). "Similarly, whereas THBS2 overexpression was associated with tumours located in the rectum, downregulated expression levels of ADH1B mRNA were more frequent in tumours situated in the colon (p = 0.02) at advanced stages (T3–T4; p = 0.04)." (PMID 36077612, 2022). "However, age, anatomic neoplasm subdivision, lymphatic invasion, tumor residual, and tumor status were all significantly different between the low ADH1B expression group and the high ADH1B expression group." (PMID 35756990, 2022). "The most consistently downregulated gene across the investigated tumor types was Alcohol dehydrogenase 1B (ADH1B), a member of the alcohol dehydrogenase enzyme subgroup which serves as an important member in the ethanol, retinol and further alcoholic substance metabolization processes." (PMID 33807717, 2021). "It is possible that the product of the ALDH3B2 gene could serve as the enzyme protecting tumor colon cells from ROS (reactive oxygen species), considering that expression of other alcohol dehydrogenase isozymes (ADH1B and ADH1C) is decreased." (PMID 30967137, 2019). "In addition, sCRC tumours also featured the downregulation of genes involved in retinol metabolism or other processes such as fatty acid degradation, glycolysis, gluconeogenesis, and drug metabolism through cytochrome P450, as in the case of the ADH1B gene." (PMID 36077612, 2022). "Up-regulation of the SPP1, miR-122, SRPX2, ADH1B, miR-21, SALL4 and PRAP1 genes, as well as down-regulation of miR-378e have been previously associated with an increased tumor cell migration capacity among sCRC, greater tumor progression potential, a metastatic phenotype and inhibition of apoptosis." (PMID 29296198, 2017). "In summary, our findings reveal that four of the identified characteristic genes (ADH1B, CCL27, ID4 and LRP4) are consistently downregulated in cSCC, and prior studies suggest their involvement in tumor proliferation, migration and invasion." (PMID 40296873, 2025).
tumor (continued). "Results showed that four prognostic genes (ADH1B, ADH4, UGT1A1, and GPX3) exhibited significantly lower expression in tumor samples compared to normal samples." (PMID 41031088, 2025). "Quantitative evaluation revealed consistent downregulation of ADH1B, CCL27, ID4 and LRP4 in tumor tissues compared to normal counterparts." (PMID 40296873, 2025). "The single-cell dataset showed significant under-expression of ADH1B, ADH4, CYP19A1, and GPX3 in tumor samples." (PMID 41031088, 2025). "Single cell analysis identified six major fibroblast subgroups; universal (PI16+) fibroblasts, ADH1B + fibroblasts and CCL19 + FRC-like fibroblasts were present in normal tissue and tumours." (PMID 39757146, 2025). "The results showed that ALDOA, ADH1B, and ALDH3B1 were significantly overexpressed in tumor samples compared to normal samples." (PMID 38256214, 2024). "The non-tumor tissue was well classified by Galphai2, CA-II, ADH1C, CEH, and IgGFc-binding protein, while ADH1B contributed with a lower MDA score." (PMID 39195201, 2024). "ALDH2, ADH1B, ALDH3A2, DPT, EPHX2, and GATM were down-regulated in the tumor tissues, which is consistent with the expression of hub genes in the GSE3189 and GSE46517 datasets." (PMID 38378847, 2024). "All-trans-retinol dehydrogenase NAD+ (ADH1B), ADH1C, and CA-II showed the lowest levels in both S and D tumor samples." (PMID 39195201, 2024). "With reduced ADH1B expression, infiltration of CD8 T cells, eosinophils, and type 1 T helper cells decreased, leading to a relevant weak ability of tumor cell killing." (PMID 37229243, 2023). "Since we identified that ADH1B expression positively correlates with ADH1B+ CAF enrichment, and it is very specific marker for ADH1B+ CAFs in the tumor microenvironment, we decided to stratify TCGA samples into ADH1B low, intermediate and high groups." (PMID 37848457, 2023). "The results of our research show that ADH1B+ CAFs correlate with LUAD behavior and can be used for the prediction of tumor aggressiveness at an early stage." (PMID 37848457, 2023). "In contrast, two genes, ADH1B and MYLK, with an established relationship with sCRC, had high levels of downregulation of tumour suppressor mRNAs." (PMID 36077612, 2022). "The SNPs of ADH1B rs1229984, ADH1C rs1789924, and ALDH2 rs671 were detected by Sanger sequencing using formalin-fixed paraffin-embedded tumor samples." (PMID 36212135, 2022). "The most consistently upregulated genes across multiple tumor types were TOP2A (FC = 7.8), SPP1 (FC = 7.0) and CENPA (FC = 6.03), and the most consistently downregulated gene was ADH1B (FC = 0.15)." (PMID 33807717, 2021). "Our results showed that the expression level of ADHs including ADH1A, ADH1B, ADH1C, and ADH6 was obviously decreased with the progression of tumor malignancy." (PMID 33287761, 2020). "The slow-metabolizing ADH1B*1/*1 genotype and the inactive heterozygous ALDH2*1/*2 genotype were significantly more common in the groups with neoplasia." (PMID 30629674, 2019). "ACACB, ADH1B, and SCD, as key genes related to FAM, play important roles in tumor progression in PTC and may serve as potential therapeutic targets in PTC patients." (PMID 40084144, 2025). "The expression of ADH1B is negatively correlated with TMB and may be a new target for tumor immunotherapy." (PMID 38256214, 2024). "In contrast, ADH1B and ALDH2 were upregulated in the early stage of tumor grade." (PMID 37540213, 2023). "The expression levels of FCGBP, PABPC1 and NDRG1 were higher and the expression levels of ADH1A, CYP3A4 and ADH1B were lower in tumour tissues than in adjacent nontumour tissues." (PMID 35109839, 2022). "However, three glycolysis-related genes (ADH1B, ADH5, and NUP210) were significantly differentially expressed at the mRNA level in tumor tissues versus adjacent normal tissues but were not significantly related to patient prognosis (p > 0.05)." (PMID 34595101, 2021).
tumor (continued). "More than half of the genes were not DE in any tumor type, while seven genes (C7, ADH1B, HSPB6, FXYD1, PLAC9, TMEM132A and ASF1B) were DE in all tumor types." (PMID 26655252, 2016). "Moreover, smoking status and/or cumulative smoking history do not provide a direct, clinically accessible proxy for tumor ADH1B expression." (PMID 38256214, 2024). "High ADH1B but low FAP expression after neoadjuvant treatment might indicate the main contribution of ADH1B + CAF to fibroblasts, potentially enhancing anti-tumor immune activity." (PMID 37537219, 2023). "However, four tumor markers (POSTN, pSMAD2/3, CXCL14, ADH1B, FAP) that have previously been reported to predict suboptimal debulking were selected in our model, although only p-SMAD2/3 was in the same direction but with lower discriminatory performance compared to prior reports." (PMID 36761962, 2023). "Most of these genes, including ADH1B, ALDH1A1, ADH1C and ALDH2, were significantly down-expressed in ER+ or ER- tumors compared to tumor-adjacent normal tissues, although none showed significant differential expression by alcohol intake in either tissue type." (PMID 28899409, 2017).
metabolic disease (3 papers, 2015 to 2025). A congenital disorder (due to inherited enzyme abnormality) or acquired (due to failure of a metabolically important organ) disorder resulting from an abnormal metabolic process. "The fact that ADH1B enzymatic activity appears critical for human adipogenesis raises the possibility that genetic variation affecting the enzyme could predispose to human metabolic disease." (PMID 38838011, 2024).
infection (2 papers, 2013 to 2024). The state of being infected such as from the introduction of a foreign agent such as serum, vaccine, antigenic substance or organism. "A custom-designed guide RNA (gRNA)/Cas9 expression vector targeting the fourth exon of ADH1B was inserted into lentiviral particles before ASC infection." (PMID 38838011, 2024).
neurodegenerative disease (2 papers, 2019 to 2022). A disorder of the central nervous system characterized by gradual and progressive loss of neural tissue and neurologic function. "PD and AD are both common neurodegenerative diseases, and our data show that ADH1B levels in PD and HC were not significantly different (p > 0.05)." (PMID 31231206, 2019).
ADH1B also shares sentences with these, for which no sentence is quoted: alcoholism (41 papers); cardiovascular disease (7); squamous cell carcinoma (3); alcohol addiction (2); Anxiety (2); bipolar disorder (2); hay fever (2); intracerebral hemorrhage (2); laryngeal carcinoma (2); lung adenocarcinoma (2); myocardial infarction (2); prediabetes (2); abdominal aortic aneurysm (1); Achalasia (1); acute coronary syndrome (1); age-related macular degeneration (1); Airway obstruction (1); angiosarcoma (1); anxiety disorder (1); aortic valve stenosis (1); atopic asthma (1); atrial fibrillation (1); bipolar disorder-II (1); cancer of larynx (1); childhood asthma (1); chronic atrophic gastritis (1); cocaine dependence (1); colon adenocarcinoma (1); colorectal (1); dependence (1).
A further 28 diseases each share a sentence with ADH1B in 1 paper.